AFG2A (AAA ATPase AFG2A)
Description:
ATP-dependent chaperone part of the 55LCC heterohexameric ATPase complex which is chromatin-associated and promotes replisome proteostasis to maintain replication fork progression and genome stability. Required for replication fork progression, sister chromatid cohesion, and chromosome stability. The ATPase activity is specifically enhanced by replication fork DNA and is coupled to cysteine protease-dependent cleavage of replisome substrates in response to replication fork damage. Uses ATPase activity to process replisome substrates in S-phase, facilitating their proteolytic turnover from chromatin to ensure DNA replication and mitotic fidelity. Plays an essential role in the cytoplasmic maturation steps of pre-60S ribosomal particles by promoting the release of shuttling protein RSL24D1/RLP24 from the pre-ribosomal particles. May be involved in morphological and functional mitochondrial transformations during spermatogenesis (By similarity).
Synonyms: SPAF; SPATA5; AFG2; EHLMRS; NEDHSB
Tractability: PROTAC: UniProt records ubiquitination sites on it; ubiquitination databases record sites on it.
Gene: Protein-coding gene on chromosome 4 (122,923,070 to 123,319,433, forward strand). Ensembl gene ENSG00000145375.
Subcellular location: Cytoplasm; Mitochondrion; Cytoplasm, cytoskeleton, spindle
Subcellular location (Human Protein Atlas): Cytosol
Gene Ontology:
Molecular function: ATP hydrolysis activity; preribosome binding; protein binding; ATP binding; protein-containing complex binding
Biological process: brain development; DNA replication; regulation of ribosome biogenesis; ribosomal large subunit biogenesis
Cellular component: ATPase complex; cytoplasm; cytosol; mitochondrion; nucleus; spindle
Genetic constraint (gnomAD): Loss-of-function variants: 63 observed, 88.58 expected, observed/expected ratio (o/e) 0.71, 90% interval 0.58 to 0.88. The upper end of that interval is the gene's LOEUF score, 0.88, which puts it in group 3 of 6, group 1 being the genes least tolerant of losing a copy. Missense variants: 982 observed, 1,092 expected, observed/expected ratio (o/e) 0.9, 90% interval 0.85 to 0.95. Synonymous variants: 364 observed, 394.77 expected, observed/expected ratio (o/e) 0.92, 90% interval 0.85 to 1.01.
Gene-disease validity (ClinGen):
ClinGen rates the evidence that AFG2A causes each of these diseases.
syndromic complex neurodevelopmental disorder (autosomal recessive): Definitive. A disorder that involves more than one phenotype associated with the central nervous system, including but not limited to intellectual disability, autism, and seizures (epilepsy), and also a distinctive pattern of other features including dysmorphisms and/or congenital malformations.
Homologues: Orthologues: chimpanzee AFG2A (99% identical), macaque AFG2A (97% identical), pig AFG2A (88% identical), dog AFG2A (86% identical), rabbit AFG2A (86% identical), guinea pig AFG2A (85% identical), mouse Afg2a (85% identical), rat Afg2a (85% identical), tropical clawed frog afg2a (64% identical), Drosophila melanogaster CG5776 (35% identical), Caenorhabditis elegans cdc-48.3 (29% identical). Paralogues in human: VCP (35% identical), NVL (32% identical), AFG2B (30% identical), PEX1 (25% identical), PEX6 (23% identical).
Diseases named in the same sentence as AFG2A in open-access papers:
AFG2A is named in the same sentence as 32 diseases in open-access papers, as found by Europe PMC text mining. Sharing a sentence is not in itself a finding about the gene and the disease. The quoted sentences say what the papers report.
Intellectual disability (6 papers, 2016 to 2026). "Of note, human genetic studies have identified a growing number of allelic variants in AFG2A, AFG2B and CINP that are specifically associated with a range of NDDs, including intellectual disabilities, seizures, hearing loss and microcephaly." (PMID 40760247, 2025). "AFG2A-RE is an ultra-rare, recessive disorder, sometimes presenting as a developmental and epileptic encephalopathy (DEE), characterised by the triad of epilepsy, congenital microcephaly, and deafness, and typically associated with intellectual disability, spasticity, and movement disorders." (PMID 41933351, 2026).
epilepsy (4 papers, 2016 to 2026). A brain disorder characterized by episodes of abnormally increased neuronal discharge resulting in transient episodes of sensory or motor neurological dysfunction, or psychic dysfunction. "OBJECTIVES: To expand the clinical features, epilepsy phenotype, and genotype in individuals with AFG2A-related encephalopathy (AFG2A-RE), previously known SPATA5-related encephalopathy, and to explore potential associations between genotype and epilepsy manifestations." (PMID 41933351, 2026).
hearing loss (3 papers, 2016 to 2025). "Neurogenetic disorders with combined developmental and auditory phenotypes, including AFG2A (SPATA5) and AFG2B (SPATA5L1)–related syndromes, are increasingly recognized within a broader spectrum of neurogenetic hearing loss." (PMID 41375745, 2025).
AFG2A also shares sentences with these, for which no sentence is quoted: microcephaly (5 papers); cancer (3); developmental delay (3); infection (3); Autoimmunity (2); breast cancer (2); Dystonia (2); hepatocellular carcinoma (2); neurodevelopmental disorder (2); Obesity (2); Azoospermia (1); Brain atrophy (1); breast (1); Cerebellar atrophy (1); ciliopathies (1); colon cancer (1); concussion (1); deafness (1); developmental and epileptic encephalopathy (1); dwarfism (1); Encephalopathy (1); infantile spasms (1); liver cancer (1); mitochondrial disease (1); movement disorder (1); neurological disease (1); Obstructive azoospermia (1); Spasticity (1); viral infection (1).